DDR2 (discoidin domain receptor tyrosine kinase 2)
Diseases named in the same sentence as DDR2 in open-access papers (continued):
Sharing a sentence is not in itself a finding about the gene and the disease.
Alport syndrome (2 papers, 2021 to 2022). A rare renal disease characterized by glomerular nephropathy with hematuria progressing to end-stage renal disease (ESRD), frequently associated with sensorineural deafness, and occasionally with ocular anomalies. "While the role of DDR1 in Alport syndrome has been studied, that of DDR2 is unknown." (PMID 33706638, 2021). "In some animal models of kidney injury like Alport syndrome and UUO, upregulation of DDR2 expression has been shown by Western blot and RT-PCR, respectively." (PMID 36249782, 2022). "Thus, unlike DDR1, DDR2 might not be critically involved in the pathogenesis of Alport syndrome." (PMID 36249782, 2022).
chronic myelogenous leukemia (2 papers, 2016 to 2022). "These four compounds were developed as inhibitors to BCR-ABL for the treatment of chronic myeloid leukaemia, but have since been found to have a number of novel kinase and non-kinase targets, including SRC and DDR2." (PMID 35406381, 2022).
cutaneous melanoma (2 papers, 2016 to 2022). A primary melanoma arising from atypical melanocytes in the skin. "Pure mutated DDR2 without evidence of an altered copy number was reported in a few malignancies including 13.8% of cutaneous squamous cell carcinomas, 6.9% of small cell lung cancers, 4.5% of uterine carcinosarcomas, and 4.1% of cutaneous melanomas." (PMID 27793038, 2016).
endometriosis (2 papers, 2022 to 2025). The growth of functional endometrial tissue in anatomic sites outside the uterine body. "This study identified DDR2 as a key hypoxia‐related gene in endometriosis, demonstrating its diagnostic and therapeutic potential through integrated analyses and experimental validation." (PMID 41424583, 2025). "DDR2 is a key hypoxia‐related gene in endometriosis and a promising diagnostic and therapeutic biomarker." (PMID 41424583, 2025). "To assess the impact of DDR2 knockdown on the proliferative capacity of endometriosis cells VK2/E6E7 and 12Z, we conducted CCK‐8 and EdU assays." (PMID 41424583, 2025). "Functional assays demonstrated that DDR2 knockdown significantly inhibited cell proliferation, migration, and invasion in the endometriosis cell lines VK2/E6E7 and 12Z." (PMID 41424583, 2025). "This interplay between DDR2 and HIF‐1α underscores the importance of targeting DDR2 in conjunction with other hypoxia‐related pathways to manage disease progression in endometriosis." (PMID 41424583, 2025). "In the merged dataset, DDR2 showed a marked differential expression between normal and endometriosis tissues." (PMID 41424583, 2025). "Within the hypoxic microenvironment characteristic of endometriosis, DDR2 likely acts in synergy with HIF‐1α, enhancing processes such as tissue remodeling and angiogenesis." (PMID 41424583, 2025). "Functional experiments revealed that DDR2 knockdown significantly suppressed endometriosis cell proliferation, migration, and invasion, highlighting its pivotal role in hypoxia‐driven pathophysiological processes." (PMID 41424583, 2025). "DDR2 was subsequently prioritized as a potential therapeutic target and subjected to experimental validation to confirm its functional significance in endometriosis." (PMID 41424583, 2025). "This study highlights DDR2 as a crucial player in the hypoxic microenvironment of endometriosis, with significant implications for both diagnosis and therapy." (PMID 41424583, 2025). "Collectively, these findings highlight DDR2′s multifaceted role in supporting the persistence, invasiveness, and progression of endometriosis, making it a key driver of the disease′s pathological features." (PMID 41424583, 2025). "In the two datasets, higher levels of BGN, AQP1, ELMO1, and DDR2 were confirmed in endometriosis than normal endometrium tissues." (PMID 36059959, 2022). "Altogether, our research determined four characteristic genes (BGN, AQP1, ELMO1, and DDR2) with the favorable efficacy in diagnosing endometriosis." (PMID 36059959, 2022). "Furthermore, animal models and clinical trials are necessary to validate DDR2′s involvement in endometriosis and to evaluate its potential as a therapeutic target." (PMID 41424583, 2025). "Taken together, DDR2′s dual role in regulating tissue remodeling and inflammation, combined with its interactions with established therapeutic targets like VEGF and HIF‐1α, positions DDR2 as a promising novel target for therapeutic intervention in endometriosis." (PMID 41424583, 2025). "In the merged dataset, the expression levels of these six genes—DDR2, ENO3, ESM1, NMBR, PRKAB1, and PRPF19—showed significant differences between normal and endometriosis samples (DDR2, p < 0.001; ENO3, p < 0.001; ESM1, p < 0.001; NMBR, p = 0.002; PRKAB1, p < 0.001; PRPF19, p < 0.001)." (PMID 41424583, 2025). "Notably, DDR2 interacts with key signaling pathways that overlap with well‐established therapeutic targets in endometriosis, such as VEGF and HIF‐1α." (PMID 41424583, 2025). "In both assays, the DDR2 knockdown groups demonstrated substantially reduced cell invasion and migration compared to the control groups, suggesting that DDR2 may be involved in the regulation of cell motility and the ability of endometriosis cells to invade surrounding tissues." (PMID 41424583, 2025).
endometriosis (continued). "Given DDR2′s role in modulating the ECM and promoting invasiveness, it is likely to act synergistically with VEGF and HIF‐1α in driving lesion progression in endometriosis." (PMID 41424583, 2025). "Through Lasso algorithm, four characteristic genes were determined among the shared endometriosis-related genes, containing BGN, AQP1, ELMO1, and DDR2." (PMID 36059959, 2022). "Through the Lasso approach, we determined four characteristic genes among endometriosis-related genes, containing BGN, AQP1, ELMO1 and DDR2." (PMID 36059959, 2022). "The AUCs (95%CI) of AQP1, BGN, DDR2, and ELMO1 were 0.96 (1.00–0.89), 0.98 (1.00–0.95), 1.00 (1.00–0.99), and 0.99 (1.00–0.98), respectively, demonstrating that each characteristic gene enabled to diagnose endometriosis accurately and sensitively." (PMID 36059959, 2022). "In the GSE141549 validation cohort, only DDR2, ESM1, and PRKAB1 maintained the same expression trends as observed in the merged dataset, with statistically significant differences between normal and endometriosis samples (DDR2, p < 0.001; ESM1, p = 0.002; PRKAB1, p < 0.001)." (PMID 41424583, 2025).
heart failure (2 papers, 2023 to 2024). Inability of the heart to pump blood at an adequate rate to meet tissue metabolic requirements. "Furthermore, we observed the proportion of markers associated with fibroblasts (VIM, POSTN, DDR2, THBS4, COL1A1, COL1A2, FN1) were significantly higher in heart failure than the control group in the human data, which were consistent with that in mice." (PMID 36805782, 2023). "Consistent with above data, cluster 1 (subtypes with high expression of extracellular matrix protein including DDR2, THBS4, FN1, POSTN) at heart failure which involved in ECM organization, extracellular structure organization." (PMID 36805782, 2023). "We stained heart sections from healthy people and patients with heart failure (with a history of hypertension and hyperlipidemia) using immunofluorescence and found that CD34 costaining for DDR2, POSTN, and FABP4 was greater in the heart failure group than in the control group." (PMID 39198543, 2024).
Insulin resistance (2 papers, 2022). Increased resistance towards insulin, that is, diminished effectiveness of insulin in reducing blood glucose levels. "Further analysis demonstrated these genes were enriched for EMT- and stemness-associated pathways, including Insulin resistance, Focal adhesion, PDGFR, and DDR2 signaling." (PMID 36319643, 2022). "Overexpressing Ddr2 in 3T3-L1 adipocytes leads to reduction of insulin-stimulated IRS-1 tyrosine phosphorylation and glucose transporter, thereby insulin resistance." (PMID 34645939, 2022).
keloid (2 papers, 2022 to 2025). An irregularly shaped, elevated mark on the skin caused by deposits of excessive amounts of collagen during wound healing. "In particular, lncRNA XLOC_000587 may participate in cell proliferation and migration by enhancing the expression of ENAH, and AF268386 may accelerate the invasive development of keloids by upregulating DDR2." (PMID 35012558, 2022). "The lncRNA, XLOC_000587 may promote cell proliferation and migration by enhancing the expression of ENAH, while AF268386 may facilitate the invasive growth of keloids by upregulating DDR2." (PMID 35012558, 2022). "According to the role of DDR2 in wound healing and metastatic spreading and the hypoxic microenvironment in keloids, we hypothesize that targeting AF268386 or the corresponding lncRNA AF268386 could be a potential therapeutic approach for keloids treatment." (PMID 35012558, 2022). "This is based on previous studies showing that DDR2 drives collagen-induced MMP14 activation in fibroblasts and that enhanced MMP14 activity in keloid fibroblasts is responsible for continued collagen deposition and keloid progression." (PMID 41259339, 2025).
metastatic cancer (2 papers, 2014). A carcinoma which has spread from the original site of growth to another anatomic site. "Apart from its important role in development and tissue repair, the DDR2 also regulates primary and metastatic cancer progression by down-streaming of the DDR2 signaling pathways including Shp-2, Src, STAT and MAPK." (PMID 25173530, 2014). "Discoidin domain receptor 2 (DDR2), is a novel receptor tyrosine kinases that respond to several collagens and involved in tissue repair, primary and metastatic cancer progression." (PMID 24885564, 2014).
metastatic melanoma (2 papers, 2016 to 2026). A melanoma that has spread from its primary site to another anatomic site. "DDR2 has been found to promote invasion in prostate, non-small cell lung, breast, and metastatic melanoma." (PMID 27014069, 2016). "Recently, Poudel and co-workers demonstrated that DDR2 was able to modulate MMP-2 and MMP-9 secretion in response to type I collagen and to regulate the invasive phenotype of murine metastatic melanoma cells through a regulation of ERK1/2 and NF-κB signaling pathways." (PMID 27014069, 2016).
Obesity (2 papers, 2019 to 2022). Accumulation of substantial excess body fat. "Targeting adipocytic Ddr2 may be a potential strategy for treating obesity and pathological bone loss simultaneously." (PMID 34645939, 2022). "Our observations unravel the potential of targeting adipocytic Ddr2 as a novel strategy for treating obesity and low-bone-mass disorders." (PMID 34645939, 2022). "Targeting adipocytic Ddr2 may be a potential strategy for treating obesity and low-bone-mass disorders." (PMID 34645939, 2022). "It will be important to determine if the myeloid-derived CD45+DDR2+ cells presented herein contribute to “M1” or “M2” macrophage populations, or a unique macrophage population in adipose tissue, and how this changes as obesity is established." (PMID 31015794, 2019). "Thus, at least in a model of preobesity, the activation status of myeloid-derived CD45+DDR2+ cells may be a useful biomarker for immune activation in the progression to obesity." (PMID 31015794, 2019). "Taken together, our data show that myeloid-derived CD45+DDR2+ cells are highly activated in HFD-fed preobese mice and suggest that a subset of these cells may be modulating the inflammatory immune response before obesity is established." (PMID 31015794, 2019).
prostate tumor (2 papers, 2019 to 2024). "Module 3 includes NTRK2, DDR2, and STAT5B, which have been associated with prostate tumor metastasis, and JAZF1, ZEB1, and BCL2, which have been linked to cancer progression and resistance to chemotherapy." (PMID 39347576, 2024). "Using a proteomic strategy based on this concept, our global proteomic analysis of CAF established from primary prostate tumors identified a prominent protein-protein interaction hub centered on the DDR2-collagen-LOXL2 signaling axis, critical for ECM remodeling and function." (PMID 31061140, 2019).
Ureteral obstruction (2 papers, 2019 to 2021). Obstruction of the flow of urine through the ureter. "Interestingly, a previous report showed that the deletion of Ddr2 in mice attenuated the renal fibrosis induced by unilateral ureteral obstruction (UUO)." (PMID 33706638, 2021).
alcoholic liver diseases (1 paper, 2013). A disorder caused by damage to the liver parenchyma due to alcohol consumption. "We constructed plasmid vectors encoding short-hairpin RNA against DDR2 to investigate its role in alcoholic liver disease in an immortalized rat hepatic stellate cell line, HSC-T6, and in rats by MTT, RT-PCR and western blot analyses; immunohistochemistry and electron microscopy." (PMID 23409069, 2013). "DDR2 may have an important role in the pathogenesis of early-stage alcoholic liver disease." (PMID 23409069, 2013). "Silencing DDR2 may be effective in preventing early-stage alcoholic liver disease." (PMID 23409069, 2013). "Inhibition of DDR2 decreased HSC-T6 cell proliferation and liver injury in rats with 10-week-induced alcoholic liver disease." (PMID 23409069, 2013).
carcinoid (1 paper, 2021). "Four additional somatic mutations were detected in the DDR2 (p.Arg806Ter), CDK6 (p.Thr107Ser), and SMARCA4 gene (p.Arg1135Gln) were identified in the adenocarcinoma component, whereas no specific mutations were identified in the carcinoid component." (PMID 34926584, 2021).
chondrodysplasia (1 paper, 2013). "Chondrodysplasia-causing mutations has been reported only for a discoidin domain receptor 2 (DDR2), which is a receptor tyrosine kinase that regulates chondrocyte differentiation and proliferation during endochondral ossification." (PMID 24086591, 2013).
colon adenocarcinoma (1 paper, 2014). "In contrast DDR2−/− mice that received intrasplenic injection of murine colon adenocarcinoma cell line MCA38 had more hepatic metastasis than equivalently treated DDR2+/+ mice." (PMID 24505276, 2014).
craniosynostosis (1 paper, 2025). Craniosynostosis is defined as the premature fusion of one or more cranial sutures leading to secondary distortion of skull shape resulting in skull deformities with a variable presentation.
diabetic cardiomyopathy (1 paper, 2022). Diabetic cardiomyopathy is a disorder of the heart muscle in people with diabetes. "The findings are important because they identify DDR2 as a molecular target of metformin, uncovering the molecular basis of its protective role in vascular fibrosis and possibly cardiac fibrosis associated with diabetic cardiomyopathy." (PMID 36614028, 2022). "The findings identify DDR2, a mediator of cardiovascular remodelling, as a molecular target of metformin, thereby uncovering the molecular basis of its protective role in vascular fibrosis and possibly cardiac fibrosis associated with diabetic cardiomyopathy." (PMID 36614028, 2022).
Fanconi anemia (1 paper, 2021). Fanconi anemia (FA) is a hereditary DNA repair disorder characterized by progressive pancytopenia with bone marrow failure, variable congenital malformations and predisposition to develop hematological or solid tumors. "Other involved pathways were again cell cycle signaling (15%, CDK6, CDK12), Fanconi anemia/DNA repair (15%, FANCD2, NBN), and additionally peroxisome proliferator-activated receptor (PPAR) signaling (8%, PPARG) as well as discoid in domain receptor 2 signaling (8%, DDR2)." (PMID 34200508, 2021).
fibrodysplasia ossificans progressiva (1 paper, 2025). Fibrodysplasia ossificans progressiva (FOP) is a severely disabling heritable disorder of connective tissue characterized by congenital malformations of the great toes and progressive heterotopic ossification that forms qualitatively normal bone in characteristic extraskeletal sites. "In addition, Ddr2 deficiency attenuates HO in mice expressing the ACVR1 mutation associated with human fibrodysplasia ossificans progressiva." (PMID 39746922, 2025).
gastric tumours (1 paper, 2022). "Together, the identification of these ECM pathways and the co-expression of AKT3 and DDR2 in E-cadherin-low gastric tumours suggest an active link between ECM remodelling and AKT3 signalling in DGC." (PMID 35406381, 2022).
head and neck cancer (1 paper, 2025). A primary or metastatic malignant neoplasm affecting the head and neck. "In head and neck cancer, dasatinib has also been shown to inhibit DDR2." (PMID 40563472, 2025).
head and neck squamous cell carcinoma (1 paper, 2018). A squamous cell carcinoma that arises from any of the following anatomic sites: lip and oral cavity, nasal cavity, paranasal sinuses, pharynx, larynx, and salivary glands. "For example, we found a TRABD–DDR2 fusion in one head and neck squamous cell carcinoma (HNSC) sample, which fused the stronger TRABD promoter with DDR2, resulting in its overexpression." (PMID 29617662, 2018).
liver diseases (1 paper, 2023). "Results from in vitro experiments suggested that DDR2 regulates the bioactivation of HSCs and the secretion of MMPs and promotes the development of fibrosis in early liver disease." (PMID 37007062, 2023). "A brief overview of the potential roles of DDR1 and DDR2 in premalignant and malignant liver diseases is presented." (PMID 37007062, 2023).
male infertility (1 paper, 2015). The inability of the male to effect fertilization of an ovum after a specified period of unprotected intercourse. "In the present study, evidence is provided for the potential involvement of Ddr2/COL1 cascade in the pathogenesis of male infertility in Ddr2slie/slie mutant mice." (PMID 26158267, 2015).
Myocardial fibrosis (1 paper, 2024). "Finally, this review focuses on Discoidin domain receptor 2 (DDR2), a collagen-activated receptor tyrosine kinase predominantly located in cardiac fibroblasts that can potentially be targeted to prevent or minimise myocardial fibrosis." (PMID 38612393, 2024).
myocardial infarction (1 paper, 2019). Gross necrosis of the myocardium, as a result of interruption of the blood supply to the area, as in coronary thrombosis. "A recent study of single cell analyses revealed the up-regulation of fibrotic gene profiles: Postn, Acta2, Adam12, Lox, Wisp1, and Ddr2 during cardiac remodeling in response to angiotensin II and after myocardial infarction." (PMID 31417912, 2019).
oral squamous cell carcinoma (1 paper, 2021). "In oral squamous cell carcinoma, downregulation of colon cancer-associated transcript 1 (CCAT1) prevents proliferation via inhibition of DDR2, resulting in inactivation of ERK/AKT pathways." (PMID 33917302, 2021). "In oral squamous cell carcinoma, downregulation of CCAT1 prevents proliferation, migration, and invasion through inhibition of DDR2 leading to inactivation of ERK/AKT pathway." (PMID 33917302, 2021).
plexiform neurofibroma (1 paper, 2025). An elongated and multinodular neurofibroma, formed when the tumor involves either multiple trunks of a plexus or multiple fascicles of a large nerve, such as the sciatic. "DDR1 and DDR2 are two of the most significantly repressed genes in plexiform neurofibroma mice after treatment with the kinase inhibitor cabozantinib." (PMID 40025071, 2025).
pulmonary adenoid cystic carcinoma (1 paper, 2015). "The data presented in this work suggest that EGFR, KRAS, BRAF, ALK, PIK3CA, PDGFRA, and DDR2 may not be driver genes in primary pulmonary adenoid cystic carcinoma." (PMID 26373952, 2015).